PTX3 (pentraxin 3)
Diseases named in the same sentence as PTX3 in open-access papers (continued):
Sharing a sentence is not in itself a finding about the gene and the disease.
systemic sclerosis (5 papers, 2016 to 2024). A chronic disorder, possibly autoimmune, marked by excessive production of collagen which results in hardening and thickening of body tissues. "The increased serum level of pentraxin 3 was associated with the disease severity of systemic sclerosis." (PMID 33233354, 2020). "The hsa‐miR‐21‐5p/PTX3 network modulated by LINC01128 regulates immune response and relevant inflammation in systemic sclerosis." (PMID 38224186, 2024).
Takayasu arteritis (5 papers, 2014 to 2021). A rare inflammatory large-vessel vasculitis primarily affecting the aorta and its major branches, but also other large vessels, causing stenosis, occlusion, or aneurysm. "Whether the circulating levels of pentraxin 3 (PTX3), an acute phase reactant (APR), are higher in active Takayasu arteritis (TAK), and if so, whether PTX3 is more accurate than C-reactive protein (CRP) in TAK activity assessment has been investigated in this study." (PMID 33529185, 2021). "We verified whether the blood concentrations of PTX3 and of C-reactive protein (CRP) in patients with Takayasu arteritis (TA) might reflect vascular wall involvement, as assessed by signal enhancement after contrast media administration, and the progression of arterial involvement." (PMID 25394473, 2014).
ulcerative colitis (5 papers, 2012 to 2024). An inflammatory bowel disease involving the mucosal surface of the large intestine and rectum. "These presented results provide evidence that PTX3 measurements can be useful in differentiating Crohn’s disease from ulcerative colitis during the diagnostic process." (PMID 37892129, 2023). "We conducted a randomized placebo-controlled trial to assess the efficacy of Spirulina (SP) supplementation on disease activity, health-related quality of life, antioxidant status, and serum pentraxin 3 (PTX-3) levels in patients with ulcerative colitis (UC)." (PMID 38424572, 2024). "Specifically, the concentration of PTX3 was increased in the group of patients with ulcerative colitis, while the S100A12 level was elevated in patients with Crohn’s disease." (PMID 37892129, 2023). "In comparison to our previous research conducted on a group of patients with ulcerative colitis (UC), those with CD exhibited reduced levels of PTX3 (2117.9 vs. 3197.05, p < 0.005) and elevated concentrations of S100A12 (79.4 vs. 39.36, p < 0.05)." (PMID 37892129, 2023). "IL-1β is one of the factors enhancing the synthesis of PTX3; therefore its elevated expression in NETs may result in upregulation of PTX3 during ulcerative colitis." (PMID 37892129, 2023). "Therefore, it was also of interest to determine the PTX3 expression patterns in inflammatory bowel diseases such as Crohn's disease and ulcerative colitis." (PMID 22347626, 2012). "As IL-6 was found to have increased expression in active Crohn's disease, but not in ulcerative colitis, it is not surprising that plasma PTX3 levels were increased in patients with only ulcerative colitis (because IL-1, but not IL-6, causes induction of PTX3 expression)." (PMID 22347626, 2012). "Patients with Crohn’s disease presented a decreased concentration of PTX3 (p < 0.005), while the level of S100A12 (p < 0.05) was increased compared to the subjects with ulcerative colitis before treatment." (PMID 37892129, 2023). "As in our previously conducted study, we assessed the levels of pro-GN, PTX3 and S100A12 in serum of patients with ulcerative colitis, and we also compared the profiles of these biomarkers among patients with CD and UC." (PMID 37892129, 2023). "In our previous study, we assessed the serum profiles of pro-GN, PTX3 and S100A12 protein in patients with ulcerative colitis." (PMID 37892129, 2023). "To achieve this, we referred to our previous research, conducted in the Department of Clinical Chemistry and Laboratory Diagnostics, in which we assessed serum pro-GN, PTX3 and S100A12 concentrations in another type of inflammatory bowel disease—ulcerative colitis (UC)." (PMID 37892129, 2023). "However, regarding the crucial differences in PTX3 and S100A12 serum profiles in patients with Crohn’s disease and ulcerative colitis, together with its varied synthesis and release during the diseases, our study indicate that these biomarkers might be useful in the differential diagnosis of IBD." (PMID 37892129, 2023).
urinary tract infection (5 papers, 2014 to 2023). "PTX3 haplotypes are associated with increased susceptibility to lung TB, P. aeruginosa infections in cystic fibrosis Caucasian patients, A. fumigatus infections in bone marrow transplanted patients, and urinary tract infections." (PMID 29204145, 2017). "As a key component of the innate immunity, Pentraxin 3 activated the downstream TLR4-MyD88 pathway during urinary tract infection." (PMID 27409608, 2016). "But levels of PTX3 have been shown to be the highest in patients with urinary tract infections than in those with pulmonary infections and abdominal infection and other infections." (PMID 25530683, 2014). "In addition, the role of PTX3 in innate resistance to pathogens, particularly in urinary tract infections was assessed." (PMID 29204145, 2017). "PTX3 is expressed by the murine uroepithelium during UPEC infections, and has been described in the bladder of patients with urinary tract infections (UTIs), however expression of this pentraxin in the human uroepithelium has not been documented yet." (PMID 30319631, 2018).
Arterial thrombosis (4 papers, 2019 to 2022). The formation of a blood clot inside an artery. "Excessive fibrin accumulation was observed in skin, liver and lung injury models in ptx3-deficient mice, while in a murine model of arterial thrombosis PTX3 released by EC inhibited platelet aggregation, dampening thrombogenesis." (PMID 31057548, 2019). "In a model of arterial thrombosis, PTX3 produced by the vessel wall had a critical protective role in the modulation of thrombus formation." (PMID 31019517, 2019). "The PTX3-mediated inhibition of the pro-thrombotic effects of fibrinogen and collagen l is responsible for the protective role described in an experimental model of arterial thrombosis." (PMID 36362273, 2022). "Fourteen patients with subsequent diagnosis of deep vein thrombosis, arterial thrombosis or pulmonary thromboembolism had significantly higher plasma levels of PTX3 than those without it (median [IQR]: 51.4 [24.6-94.4] versus 21 [13.4-55.2]; Mann-Whitney test P=0.049)." (PMID 36389697, 2022). "However, in arterial thrombosis PTX3 did not influence P-selectin-dependent platelet-leukocyte and platelet-endothelium aggregation." (PMID 31019517, 2019).
astrocytoma (4 papers, 2022 to 2025). "The influence of CAPE on the secretion of cytokines (IL-8, IL-10, IL-26), metalloproteinases (MMP-1, -2, -3), and pentraxin-3 (PTX3) was assessed in CCF-STTG1 astrocytoma cells stimulated with LPS and/or IFN-α under normoxic and hypoxic conditions." (PMID 41515435, 2025).
bladder cancer (4 papers, 2019 to 2024). "In this study we used biopsies and data mining to assess that PTX3 is differentially expressed during the different stages of bladder cancer (BC) progression." (PMID 31480336, 2019). "PTX3 also has suppressive effects on the progression of bladder cancer." (PMID 35053442, 2022).
brain tumors (4 papers, 2023 to 2025). "Several studies on brain tumors have consistently shown an association between PTX3 expression and inflammation within the tumor microenvironment." (PMID 39594709, 2024). "Further studies are needed to better understand the mechanisms and molecular pathways in which PTX3 is involved in malignant brain tumors, including GB, to develop new targeted therapeutic strategies." (PMID 38730589, 2024). "In recent years, PTX3 has also gained great attention in the complex scenario of brain tumors, including GB, due to its pivotal role in innate immunity and inflammatory response." (PMID 38730589, 2024). "As an essential regulator of the immune system and inflammation, the glycoprotein PTX3 has an emerging critical role in brain tumors." (PMID 38730589, 2024). "The current study demonstrated that Ptx3 expression correlates with cell invasion via the NFκB pathway, regulating AHGEF7 and Rac1 expression in brain tumors." (PMID 36633805, 2023). "For instance, elevated expression of PTX3 and other inflammatory genes has been observed in brain tumor tissues compared to adjacent non-tumor tissues." (PMID 39594709, 2024).
colon carcinoma (4 papers, 2021 to 2024). "Clinically, higher PTX3 expression was positively correlated with fibroblasts and inflammatory response signatures and associated with a poor survival outcome in colon cancer patients." (PMID 38243273, 2024). "Open-access databases were utilized to examine the association of PTX3 expression and the fibroblast signature in colon cancer." (PMID 38243273, 2024). "Similar associations between PTX3 expression and tumor-associated macrophages have also been observed in colon cancer." (PMID 39594709, 2024). "In colon cancer, except for the observations of the epigenetic regulation of PTX3 gene expression and the association of a higher plasma PTX3 level with a poor survival prognosis, the precise clinical and cellular effects of PTX3 expression remain unclear." (PMID 38243273, 2024). "Hence, it is imperative to investigate whether PTX3-induced pyroptosis plays a functional role in tumorigenesis, particularly in the context of its association with PTX3-induced anti- and protumor effects during the progression of colon cancer." (PMID 38243273, 2024). "Inhibiting PTX3 led to a reduction in colon tumor growth in vivo, which was correlated with a decrease in M2-like macrophage infiltration and an increase in cytotoxic CD8+ T-cell infiltration." (PMID 38243273, 2024). "Although PTX3 expression is attenuated in colon cancer cells, it has been shown that increased plasma PTX3 is positively correlated with a poor survival outcome." (PMID 38243273, 2024). "Our investigation into PTX3's role in promoting M2 macrophage polarization in colon cancer sheds light on its functional involvement in modulating immunosuppression within the tumor microenvironment." (PMID 38243273, 2024). "The results demonstrated enrichment of inflammation-related signaling pathways, stromal activation-related signaling pathways, and inflammatory responses in PTX3-high colon tumors compared to PTX3-low tumors." (PMID 38243273, 2024). "The decrease of the M2 macrophage population and an increase of the cytotoxic CD8+ T-cell population were observed following PTX3 inactivation in allografted colon tumors." (PMID 38243273, 2024). "To investigate the involvement of PTX3 in and its effects on stroma-mediated colon tumor growth, we employed tamoxifen-induced Ptx3 conditional knockout mice [Ptx3fl/fl and Ptx3fl/fl;Ubc-Cre mice, previously established by our group]." (PMID 38243273, 2024). "PTX3 contributes to stromal cell-mediated protumor immunity by increasing M2-like macrophage polarization, and inhibition of PTX3 with WHC-001 is a potential therapeutic strategy for colon cancer." (PMID 38243273, 2024). "We further investigated the differences in and inducibility of PTX3 expression in fibroblasts and colon cancer cell lines." (PMID 38243273, 2024). "In this study, we first demonstrated that PTX3 is mainly expressed by stromal cells and contributes to immunosuppression through activation of M2 macrophages in colon cancer." (PMID 38243273, 2024). "In our study, we observed predominant expression of PTX3 in stromal cells within the colon tumor microenvironment." (PMID 38243273, 2024). "The results of our experiments with the PTX3 inhibitor WHC-001 supported the idea that disruption of the PTX3/CD44 interaction suppresses colon cancer progression in vivo." (PMID 38243273, 2024). "Surprisingly, the results indicated that treatment with WHC-001 still inhibited MC38 tumor growth, suggesting that PTX3 is a potential therapeutic target in colon cancer." (PMID 38243273, 2024). "In this study, we offered a new perspective on how PTX3 modulates immunosuppression by promoting M2 macrophage polarization in the context of colon cancer." (PMID 38243273, 2024). "This suggests that PTX3 contributes to the immunosuppressive conditions in the microenvironment of colon cancer." (PMID 38243273, 2024).
colon carcinoma (continued). "Compared to those in CCD-18Co human colon fibroblasts and mouse embryonic fibroblasts (MEFs), the transcript and protein levels of PTX3 were very low or negligible in human and mouse colon cancer cell lines." (PMID 38243273, 2024). "Accordingly, high values of CA-19.9, TNF-α, PCT, PTX-3, and CRP were found to pose a high risk for colon cancer." (PMID 33776564, 2021). "Meanwhile, PTX-3 levels were positively correlated with the NF-κB and IL-6 levels in the breast and colon cancer." (PMID 33776564, 2021). "In our analysis of the colon cancer TCGA dataset, we observed that PTX3-high tumors expressed higher levels of the M2 macrophage signature genes and lower levels of the CD8+ T-cell signature genes, implying that PTX3 contributes to a protumor immune microenvironment." (PMID 38243273, 2024). "Although neither PTX3 expression nor the fibroblast signature score was associated with an advanced stage of colon cancer in TCGA, PTX3 expression was positively correlated with the fibroblast signature score in stage 2, 3, and 4 tumors." (PMID 38243273, 2024). "Loss-of-function assays, including studies in tamoxifen-induced Ptx3 knockout mice and treatment with an anti-PTX3 neutralizing antibody (WHC-001), were conducted to assess the involvement of PTX3 in colon cancer progression as well as its immunosuppressive effect." (PMID 38243273, 2024). "Notably, previous reports indicated that the PTX3 promoter tends to undergo extensive methylation and subsequent inactivation via epigenetic regulation in colon cancer cells, shedding light on a possible explanation for our observations." (PMID 38243273, 2024). "Therefore, targeting PTX3 with WHC-001 emerges as a promising therapeutic strategy for colon cancer." (PMID 38243273, 2024). "PTX3-high colon tumors exhibited a high fibroblast signature score, and similarly, fibroblast-high colon tumors exhibited higher PTX3 expression, consistent with the results of single-cell data analysis that identified fibroblasts as the primary source cells of PTX3 in colon tumors." (PMID 38243273, 2024). "In this study, we have demonstrated that circulating NF-κB, TNF-α, IL-6, PTX-3, PCT, and CRP levels in breast and colon cancer were significantly higher than in control groups and NF-κB levels were positively correlated with IL-6, PTX-3, PCT, and CRP in all patients." (PMID 33776564, 2021). "Given that PTX3 has been reported to enhance polarization toward the anti-inflammatory macrophage phenotype, we hypothesized that PTX3 might regulate the phenotypes of myeloid cells in colon tumors." (PMID 38243273, 2024). "PTX-3 is mainly induced by NF-κB and proinflammatory cytokines, such as IL-6 and TNF-α in breast and colon cancer." (PMID 33776564, 2021). "We observed that in subjects with breast and colon cancer, the CRP, PTX-3, and PCT levels were significantly and consistently higher than in the control group." (PMID 33776564, 2021). "PTX-3, CRP, and PCT levels have been investigated to predict the development of inflammation in various cancers, including breast and colon cancer." (PMID 33776564, 2021). "To identify the primary cell types producing PTX3 in colon tumors, we analyzed single-cell data from the Human Colon Cancer Atlas (c295), which encompasses 371,223 malignant and nonmalignant cells, on the Single Cell Portal platform." (PMID 38243273, 2024). "The serum NF-κB, TNF-α, IL-6, PTX-3, PCT, and serum CRP concentration was significantly higher, and the serum sTRAIL concentration was significantly lower in the patients with breast and colon cancer than in healthy controls." (PMID 33776564, 2021). "PTX3 mRNA expression and protein levels were significantly induced by IL-1β and TNF-α in human and mouse fibroblasts but not in colon cancer cells." (PMID 38243273, 2024).
congenital heart disease (4 papers, 2012 to 2022). A heart disease that is present at birth. "In this study, we investigated the kinetics of PTX3 in children in the early period after surgery for congenital heart disease with the use of CPB." (PMID 35989325, 2022). "Plasma PTX3 concentrations were evaluated in 50 PAH patients (27 with idiopathic PAH, 17 with PAH associated with connective tissue disease (CTD-PAH), and six with congenital heart disease), 100 age and sex-matched healthy controls, and 34 disease-matched CTD patients without PAH." (PMID 23029266, 2012). "The aim of this prospective study was to determine the early postoperative kinetics of pentraxin 3 (PTX3) in relation to PCT and CRP in children undergoing congenital heart defects surgery with CPB." (PMID 35989325, 2022).